CAPN1 (calpain 1)
Diseases named in the same sentence as CAPN1 in open-access papers (continued):
Sharing a sentence is not in itself a finding about the gene and the disease.
breast cancer (continued). "Patients with high caspase-3/high calpain-1 expression, high caspase-3/high calpain-2 expression, high caspase-3/low calpastatin expression, or high caspase-8/low calpain-1 expression had significantly worse breast cancer-specific survival (P = 0.005, 0.049, 0.02, and 0.02 respectively)." (PMID 27798717, 2017). "Another possible theory might be due to the genetic difference between the population in the current study and the published ones, which may affect the expression of calpain-1 in breast cancer cells." (PMID 28536704, 2017). "In addition to breast cancer, calpain-1 and calpain-2 expression has been shown to be altered in a number of other tumour types such as ovarian, pancreatic and gastric." (PMID 25539577, 2014). "The involvement of calpain-1 in regulation of TZ sensitivity and survival pathway by regulating cleavage and activity of ERBB2 in breast cancers has been recently investigated." (PMID 27863425, 2016). "Intriguingly, these analyses did not reveal a significant correlation between CAPN1 expression levels and breast cancer survival rates." (PMID 40744683, 2025). "Other studies have shown that cisplatin-induced apoptosis of triple negative MB-231 breast cancer cells takes place through the calpain-1-mediated cleavage of caspase-12." (PMID 37795261, 2023). "The expression of calpain-1, calpain-2 and calpastatin was determined using immunohistochemistry on core biopsy samples, in a cohort of large but operable inflammatory and non-inflammatory primary breast cancer patients treated with neoadjuvant chemotherapy." (PMID 27323818, 2016). "However, this pronounced differential expression does not correlate significantly with breast cancer prognosis, suggesting that while CAPN1 may be involved in the etiology or progression of breast cancer, its direct impact on patient outcomes is not definitive." (PMID 40744683, 2025).
Alzheimer disease (8 papers, 2011 to 2024). A progressive, neurodegenerative disease characterized by loss of function and death of nerve cells in several areas of the brain leading to loss of cognitive function such as memory and language. "In agreement with our results, perturbations in the activity of other members of the calpain family (e.g., calpain 1) have been associated with the neuropathological processes contributing to Alzheimer's disease." (PMID 21629698, 2011). "A third pathway affected by calpain-1 deletion is the Alzheimer’s disease pathway, with significant decrease in IDE and PER2." (PMID 32328086, 2020). "Our results underscore the important role of calpain-1 in brain development, synaptic plasticity, protein quality control and in the regulation of neuronal death and in Alzheimer’s disease." (PMID 32328086, 2020). "Moreover, based on the PPI network, PTPN1 has direct interactions with GSK3B, PIK3R1, and CAPN1 in the Alzheimer’s disease pathway." (PMID 38612872, 2024). "While calpain has been proposed to participate in various disorders related to abnormal protein folding, including Alzheimer’s disease, Parkinson’s disease, and Huntington’s disease, the specific roles of calpain-1 in these disorders have rarely been addressed." (PMID 32328086, 2020). "Our results indicate that calpain-1 regulates a much wider set of genes in brain than in muscle, and that these genes belong to signaling pathways involved among others in protein quality control and Alzheimer’s disease." (PMID 32328086, 2020). "According to the Alzheimer’s disease pathway (hsa05010), we listed the main AO targets that regulate tau phosphorylation, such as MAPT, GSK3B, CDK5, CDK5R1, and CAPN1." (PMID 36533181, 2022). "ADAM17, BACE1, CAPN1, CDK5, EIF2AK3, GRIN2B, and GSK3B were enriched in the Alzheimer disease pathway (hsa05010)." (PMID 33807157, 2021).
melanoma (8 papers, 2013 to 2023). A malignant, usually aggressive tumor composed of atypical, neoplastic melanocytes. "To assess whether the loss of CAPN1 in melanoma cells could also stabilize NF1 levels and reduce melanoma cell proliferation, we used small interfering RNA (siRNA) to deplete CAPN1 in both A375 and 74T melanoma cells." (PMID 30131853, 2018). "This novel mechanism for regulating NF1 in melanoma provides a molecular basis for targeting CAPN1 to suppress Ras activation." (PMID 32850962, 2020). "In lung cancer cells, for example, transforming growth factor-β1 was showed to induce EMT via calpain-1 and in melanoma cells calpain-4 knockdown was able to decrease cell migration and invasion." (PMID 30448882, 2019). "Active calpain-1 cleaved filamin A, which resulted in melanoma cells cytoskeletal changes and enhanced motility." (PMID 27571105, 2016). "Wnt5A activates calpain-1, leading to the cleavage of filamin A, which results in a remodeling of the cytoskeleton and an increase in melanoma cell motility." (PMID 23388158, 2013). "In that sense, calpain-1 activity was shown to be important in the treatment of other types of cancer such as myelodysplastic syndrome colorectal cancer or melanoma." (PMID 37795261, 2023). "Given that Calpain inhibitor I expression leads to increased NF1 stability and RAS inhibition and the strong contribution of the RAS pathway to promoting tumorigenesis, we reasoned that NF1 and CAPN1 expression levels may affect melanoma patient survival." (PMID 30131853, 2018). "Next, we tested the effect of CAPN1 knockdown on melanoma cell proliferation." (PMID 30131853, 2018). "In particular, we hypothesized that inhibition of MEK and upregulation of NF1 levels, by CAPN1 inhibition, might have a synergistic effect on melanoma cells." (PMID 30131853, 2018). "Regarding therapy, a study revealed Calpain1 (CAPN1), a calcium-dependent neutral cysteine protease, as a novel NF1 binding partner that regulates NF1 degradation in melanoma cells." (PMID 32850962, 2020). "ShRNA-mediated knockdown of CAPN1 or treatment with a CAPN1 inhibitor showed to stabilize NF1 protein levels, downregulate AKT signaling and melanoma cell growth." (PMID 32850962, 2020). "This novel mechanism for regulating NF1 in melanoma provides a molecular basis for targeting CAPN1 in order to stabilize NF1 levels and, in doing so, suppressing Ras activation; this mechanism can be exploited therapeutically in melanoma and other cancers." (PMID 30131853, 2018). "Immunoblotting confirmed the specific targeting of CAPN1 by shRNAs, NF1 stabilization, as well as a reduction in pAKT-308 and pAKT-473 in both melanoma cell lines, while ERK activation remained unchanged." (PMID 30131853, 2018). "ShRNA-mediated knockdown of CAPN1 or treatment with a CAPN1 inhibitor stabilizes NF1 protein levels, downregulates AKT signaling and melanoma cell growth." (PMID 30131853, 2018). "Utilizing a mass spectrometry analysis of NF1 binding partners, we revealed Calpain1 (CAPN1), a calcium-dependent neutral cysteine protease, as a novel NF1 binding partner that regulates NF1 degradation in melanoma cells." (PMID 30131853, 2018). "The fact that CAPN1 inhibition has growth inhibitory effects on NF1 wild-type and as well on NF1 mutant melanoma cell lines could have a beneficial therapeutic potential." (PMID 30131853, 2018). "As NF1 is a tumor suppressor gene, we were interested in investigating whether CAPN1 could degrade NF1, which would reveal a new mode of regulation of NF1 in melanoma, in addition to the degradation of NF1 by the ubiquitin-proteasome pathway." (PMID 30131853, 2018). "A distinct mechanism for Wnt5a induction of melanoma cell motility is through binding to Ror2 and activating of Wnt/Ca+2 signaling, leading to activation of calpain-1, a calcium-dependent non-lysosomal cysteine protease." (PMID 27571105, 2016).
melanoma (continued). "To determine whether CAPN1 directly affects NF1 stability, we treated A375 or 74T melanoma cells with increasing concentrations of Calpain inhibitor I. A significant increase in NF1 levels was observed following the inhibitory treatment, suggesting that CAPN1 is indeed involved in NF1 stability." (PMID 30131853, 2018).
diabetes (7 papers, 2020 to 2026). "The current study was designed to determine the relevance of platelet-derived calpain 1 (CAPN1) in the vascular complications associated with diabetes by identifying new calpain target proteins on the surface of endothelial cells." (PMID 33258989, 2020). "Thus, platelet-derived CAPN1 contributes to the initiation of the sterile vascular inflammation associated with diabetes via the cleavage of PAR-1 and the release of TNF-α from the endothelial cell surface." (PMID 33258989, 2020). "Calpain-1 and calpain-2 protein expression and activity in cardiac mitochondria is known to be increased in diabetes leading to myocardial injury and dysfunction." (PMID 37569859, 2023). "Our laboratory and other laboratories reported that calpain-1 aggravated diabetes-induced and arsenic-induced VED." (PMID 35983375, 2022). "In response to pathological conditions including ischemia/reperfusion (or hypoxia/reoxygenation), diabetes and sepsis, the protein levels and activity of calpain-1 and/or calpain-2 have been reported to increase in the mitochondria of cardiomyocytes and heart tissues." (PMID 34440793, 2021). "Also in mice, calpain inhibition and the platelet-specific deletion of CAPN1 both prevented the diabetes-induced increase in circulating EPCR as well as the associated vascular inflammation." (PMID 33258989, 2020). "Notably, our previous studies in mouse models of endotoxemia and diabetes demonstrated that both lipopolysaccharides (LPS) and diabetic conditions induced translocation of calpain-1 to mitochondria in cardiomyocytes, which elicits excessive mitochondrial ROS production and myocardial dysfunction." (PMID 34440793, 2021). "The importance of platelet-derived CAPN1 in the vascular complications of diabetes was demonstrated by the fact that diabetes induction in CAPN1ΔPF4 mice failed to increase circulating levels of the EPCR or to alter the surface expression of PAR-1 or ICAM-1 on endothelial cells." (PMID 33258989, 2020). "Therefore, diabetes-induced changes in PAR-1 and ICAM-1 expression were studied in animals specifically lacking CAPN1 in platelets." (PMID 33258989, 2020). "The CAPN1ΔPF4 mice were also protected from diabetes-induced vascular inflammation as while STZ-treatment resulted in a decrease in PAR-1 and an increase in ICAM-1 expression in aortic endothelial cells from wild-type mice no such changes were observed in aortae from mice lacking platelet CAPN1." (PMID 33258989, 2020).
Sepsis (6 papers, 2013 to 2025). Sepsis is defined as life-threatening organ dysfunction caused by a dysregulated host response to infection. "Herein, we have demonstrated, for the first time, that calpain-1 inhibition reduces the loss of essential cardiac cytoskeletal (dystrophin and β-dystroglycan) and contractile (sarcomeric actin and myosin) proteins during sepsis." (PMID 27880847, 2016). "Cultured neonatal mice cardiomyocytes subjected to serum obtained from mice with severe sepsis presented striking increment of [Ca2+]i and calpain-1 levels associated with decreased expression of dystrophin and disruption and derangement of F-actin filaments and cytoplasmic bleb formation." (PMID 23935889, 2013). "Cultured neonatal mouse cardiomyocytes subjected to serum obtained from mice with severe sepsis presented strikingly higher [Ca2+]i and calpain-1 levels associated with decreased expression of dystrophin and disruption and derangement of F-actin filaments and cytoplasmic bleb formation." (PMID 23935889, 2013). "At the same time, the myocardial structure is damaged after sepsis, manifested as calcium overload, increased expression of calpain-1, and enzymatic degradation of actin and myosin, inducing myocardial injury and apoptosis and leading to SIMD." (PMID 40041174, 2025). "In several diseases, proteolysis is activated inside the diaphragm and modulated by different pathways: Calcium dependent protease-based proteolysis via caspase 3 and calpain 1 have been described during sepsis, disuse (VIDD) and in chronic lung disease." (PMID 33737702, 2021). "In conclusion, HIPK2 protected the liver from sepsis-induced injury through calpain 1-mediated autophagy." (PMID 30154452, 2018). "In the present study, the levels of calpain 1 and cleaved Atg5 and the phosphorylation/activity of mTOR were significantly increased in the livers of mice with sepsis." (PMID 30154452, 2018). "Severe sepsis significantly increased heart calpain-1 levels and promoted ubiquitin and Pa28β over-expression with a reduction in the mTOR levels." (PMID 27880847, 2016). "Based on these results, it has become essential to assess the mTOR protein levels involved in the control of protein synthesis, metabolism and cell cycle in an attempt to correlate these findings with calpain-1 activation during sepsis." (PMID 27880847, 2016). "HIPK2 may inhibit calpain 1 activity and expression under normal conditions by interacting with calpain 1, and in response to sepsis, HIPK2 dissociates from calpain 1 and then interacts with calmodulin to decrease Ca2+ levels." (PMID 30154452, 2018). "Moreover, the interaction of HIPK2 with calpain 1 was reduced in mice with sepsis-induced liver injury, and the interaction of HIPK2 with calmodulin was enhanced in septic mice." (PMID 30154452, 2018). "Similarly, treatment with dantrolene decreased cardiac calpain-1 amounts at either at 6 or 24 hours after severe sepsis induced by CLP in comparison with sham-operated and sham-operated treated animals." (PMID 23935889, 2013). "Severe sepsis induced in mice led to increased expression of calpain-1 in cardiomyocytes." (PMID 23935889, 2013). "Severe sepsis induced in mice led to an increased expression of calpain-1 in cardiomyocytes." (PMID 23935889, 2013). "In addition, our results demonstrate that calpain-1 also plays a key role in protein breakdown under septic conditions, which would act as a mechanism of protein synthesis disruption, thus increasing the degree of cardiac dysfunction and injury due to sepsis." (PMID 27880847, 2016). "HIPK2 overexpression reduced the sepsis-mediated increase in calpain 1 and cleaved Atg5 levels but did not affect mTOR levels." (PMID 30154452, 2018). "Non-treated mice submitted to severe sepsis (SSI) displayed increased expression of calpain-1 by 102% when compared with the SHAM group (2.02±0.61 vs. 1.00±0.00)." (PMID 27880847, 2016).
Sepsis (continued). "There are few data in the literature showing an association between calpain-1 and the UPS in cardiac dysfunction during sepsis, and there are no reports evaluating this relationship with structural and contractile protein expression in septic myocardium." (PMID 27880847, 2016). "Based on these data, HIPK2 may inhibit calpain 1 activity under normal conditions by interacting with calpain 1, and in response to sepsis, HIPK2 dissociates from calpain 1 and then interacts with calmodulin to decrease Ca2+ levels, resulting in attenuation of sepsis-induced liver injury." (PMID 30154452, 2018).
cardiac hypertrophy (5 papers, 2017 to 2026). "The remaining 30% presented cardiac hypertrophy+dilated hearts (HD group), decreased dystrophin and increased calpain-1 expression associated with systolic and diastolic dysfunction." (PMID 29267303, 2017). "This study was undertaken to evaluate dystrophin and calpain-1 in the transition from compensated cardiac hypertrophy to HF." (PMID 29267303, 2017). "AS-IV has been demonstrated to improve cardiac function and decrease myocardial hypertrophy in several in vivo studies by decreasing oxidative stress and activating calpain-1, inhibiting the TBK1/PI3K/AKT signaling pathway, and several other additional mechanisms." (PMID 35859295, 2022).
ischemia (5 papers, 2016 to 2023). A hypoperfusion of the BLOOD through an organ or tissue caused by a PATHOLOGIC CONSTRICTION or obstruction of its BLOOD VESSELS, or an absence of BLOOD CIRCULATION. "The present study aims to investigate the potential mechanism of downregulation of Calpain 1 and 2 activity by calpeptin in the ischemia/reperfusion (IR)-induced AKI model." (PMID 35155498, 2022). "In conclusion, this study shows that the inhibition of Calpain 1 and 2 activity by calpeptin plays a nephroprotective role in ischemia/reperfusion-induced acute kidney injury by suppressing AIM2 and NLRP3 inflammasome activation and by upregulating Klotho protein." (PMID 35155498, 2022). "Calpain-1 mediated gephyrin cleavage can occur within 1 min in hippocampal membranes, and cleavage products are increased following in vitro ischemia at 30 min and up to 48 h following ischemic events in vivo." (PMID 31080408, 2019). "In this study, our in vivo and in vitro data showed that IL-17 A maintained and augmented ischemia-induced neurogenesis through the inhibition of calpain 1 activity during stroke recovery, which suggests an essential role of calpain 1 in IL-17 A-mediated neurogenesis after stroke." (PMID 27336717, 2016). "As a member of calpain protein superfamily, CAPN1 activation has been demonstrated to degrade cytoskeleton proteins, vital enzymes, and mitochondrial membrane-related proteins, which may play a primary role in ischemia-induced neuronal injury." (PMID 37168851, 2023). "In addition, calpain 1/2 play opposite roles in retinal ganglion cell (RGC) degeneration induced by ischemia/reperfusion injury, while degeneration of RGCs could lead to impaired circadian rhythmicity." (PMID 36404298, 2022).
Parkinson disease (5 papers, 2020 to 2025). A progressive degenerative disorder of the central nervous system characterized by loss of dopamine producing neurons in the substantia nigra and the presence of Lewy bodies in the substantia nigra and locus coeruleus. "In the 6-OHDA-induced Parkinson’s disease mouse model, Capn1 activation improves motor and cognitive functions." (PMID 41099906, 2025). "Increasing evidence has linked calpain-1 and calpain-2 to stroke, TBI, and AD, spinal cord injury, Parkinson’s disease (PD), and global neurodegeneration." (PMID 40940713, 2025).
triple-negative breast carcinoma (5 papers, 2017 to 2025). An invasive breast carcinoma which is negative for expression of estrogen receptor (ER), progesterone receptor (PR), and human epidermal growth factor receptor 2 (HER2). "In order to investigate the possibility of using calpain-1 protein as a prognostic biomarker in triple-negative breast cancer, its expression was assessed for association with a number of clinicopathological variables." (PMID 28536704, 2017). "To study this, we employed CRISPR-Cas9 gene editing to manipulate calpain-1/2 expression in the highly metastatic human MDA-MB-231 triple-negative breast cancer cell line." (PMID 40940726, 2025). "Our findings are consistent with these studies in which we showed that calpain-1 was significantly expressed by triple-negative breast cancer tissue at variable intensity ranking from low to high." (PMID 28536704, 2017). "However, in either luminal or triple negative breast carcinoma cell lines talin-1 was proteolyzed only by calpain-1 (Rodríguez-Fernández, 2019) (right)." (PMID 37795261, 2023). "Our study was the first to assess the proliferating and apoptotic index in triple-negative breast cancer (TNBC) tissue and to determine its correlation to calpain-1 expression." (PMID 28536704, 2017). "The aim of the current study is to assess the proliferating/apoptotic index in triple-negative breast cancer (TNBC) tissue and correlate it to calpain-1 expression." (PMID 28536704, 2017). "Therefore, we have generated a panel of CRISPR-Cas9 KO MDA-MB-231 triple-negative breast cancer cell lines for CAPN1, CAPN2, or CAPNS1 genes, which provide models for complete pharmacological inhibition of calpain-1, calpain-2, or both, respectively." (PMID 40940726, 2025).